ENSG00000285991 (novel transcript)
Gene: Protein-coding gene on chromosome 6 (149,817,937 to 149,896,011, reverse strand). Ensembl gene ENSG00000285991.
Genetic constraint (gnomAD): Missense variants: 275 observed, 284.47 expected, observed/expected ratio (o/e) 0.97, 90% interval 0.88 to 1.07. Synonymous variants: 92 observed, 102.28 expected, observed/expected ratio (o/e) 0.9, 90% interval 0.76 to 1.07.